CXCL10 (C-X-C motif chemokine ligand 10)
Diseases named in the same sentence as CXCL10 in open-access papers (continued):
Sharing a sentence is not in itself a finding about the gene and the disease.
tumor (continued). "Moreover, upon antigenic activation in vitro, PB CAR-T cells released lower levels of IFN-γ, IL-6, IL-10, TNF-α, CCL2, CXCL10, and GM-CSF than Lenti CAR-T cells, but demonstrated a robust release of IL-9, indicative of a distinct anti-tumor response pathway." (PMID 37228617, 2023). "The results demonstrated that although CXCL9- and CXCL11-expressing cells showed anti-tumor effects, CXCL10-expressing cells failed to exert anti-tumor effects." (PMID 37218983, 2023). "Secondly, RT can regulate the TME, effectively promote the infiltration of CD8+ T lymphocytes by increasing the levels of chemokines CXCL10 and CXCL16 in TME, and reducing immune-related suppressor cells in the tumor stroma, shifting the TME transition from cold tumor to the hot tumor." (PMID 36875059, 2023). "CXCL10 might also promote Th1 immune response and lead to increased number of CD8+ T cells in the inflamed tumor microenvironment." (PMID 37484803, 2023). "Tumorigenesis increased the frequency of cDC2s that were producing Cxcl10 or Cxcl9 and Cxcl10 in the dLN and tumor, yet not the spleen." (PMID 36472588, 2023). "However, IP-10 can also act the opposite way, when autocrine secretion and CXCL10/CXCR3 signaling by cancer cells support tumor cell proliferation, angiogenesis, and metastasis, inhibiting cancer cells’ apoptosis and immune response." (PMID 37509653, 2023). "Of note, CXCL10 is a pivotal inflammatory CXC chemokine in many physiological and pathological processes, including angiogenesis, chronic inflammation, immune dysfunction, tumor development and dissemination, in which ACKR2 was also shown to be involved." (PMID 37153591, 2023). "CXCL10, CXCL5, MMP1, CXCL12, CXCL11, CXCL2, STAT1, IL‐6 and TLR2 were hub genes, which may drive the homing of immune cells in tumours and promote immune cell differentiation." (PMID 36524848, 2023). "Thus, the relationship between CXCL9, CXCL10, CXCL11/CXCR3 axis and tumor development or patient prognosis is still controversial." (PMID 38264648, 2023). "Using multiplex immunoassays, we examined type I IFN (IFN-α, IFN-β), type II IFN (IFN-γ), proinflammatory cytokine (GM-CSF, IL-6, IL-12p70), and proinflammatory chemokine (CXCL10 [IP-10], CCL2 [MCP-1], CCL3 [MIP-1α], CCL5 [RANTES]) signaling in the tumor microenvironment (TME)." (PMID 36810257, 2023). "CXCL10, CXCL5, MMP1, CXCL12, CXCL11, CXCL2, STAT1, IL‐6 and TLR2 were hub genes in network and may promote or inhibit the homing or of immune cells in tumours and immune cell differentiation, bring intratumoral immune heterogeneity." (PMID 36524848, 2023). "Similarly, tumor cell-derived TGF-β signaling can trigger the release of several cytokines from CAFs, such as IL-6, CXCL10, and CCL5, which, in turn, drive the upregulation of glycogen metabolism in tumor cells through phosphoglucomutase 1 (PGM1) activation." (PMID 38002286, 2023). "In general, CXCR3 is highly expressed on the surface of NK cells, and it drives NK cell-specific chemotaxis toward the CXCR3 ligands CXCL9, CXCL10 and CXCL11, which are secreted by tumor cells into TME and usually expressed at relative low levels in homeostatic condition." (PMID 38264648, 2023). "We found that the interaction between macrophages and effector CD8+T cells through the CXCL10/CXCR3 pathway in the tumor microenvironment (TME) of the non-ablation zone was required." (PMID 36900218, 2023). "This increased CXCL10 induction correlated with higher frequency of intratumoral CXCR3+ CD8+ T cells, demonstrating that reversal of epigenetic silencing of STING using a demethylating agent can promote tumor infiltration of CD8+ T cells." (PMID 36949064, 2023). "The results indicate that although CXCL9- and CXCL11-expressing SCCs exert anti-tumor activity, the CXCL10-expressing SCC failed to exert anti-tumor activity." (PMID 37218983, 2023).
tumor (continued). "CXCL10/CXCR3 mainly activates downstream signaling pathways (including MAPK and PI3K/Akt) and then produces biological effects, such as promoting angiogenesis and inhibiting tumor-related immunity." (PMID 36782176, 2023). "Besides, both CXCL10 and LAMP3 expression in the tumor tissues indicated favorable OS in the training cohort (p = 0.006, p = 0.001, respectively) and validation I cohort (p = 0.029, p = 0.005, respectively)." (PMID 37082269, 2023). "The results showed that CXCL9- and CXCL11-expressing cells markedly inhibited tumor growth, whereas CXCL10-expressing cells did not inhibit growth." (PMID 37218983, 2023). "Tumor cells also underwent significant changes after mANK-101 treatment, including increased expression of proinflammatory chemokines CXCL9 and CXCL10, and upregulation of genes responsible for antigen processing and MHC I presentation, likely mediated by IFN-γ signaling through STAT1." (PMID 38063196, 2023). "Given the upregulation of CXCR3 on ex vivo expanded NK cells and their ability to migrate towards tumors expressing exogenous CXCL10, STING agonists could enhance their tumor homing." (PMID 38022679, 2023). "CXCL9- and CXCL11-expressing cells showed significant anti-tumor activity, while CXCL10-expressing cells failed to exert an anti-tumor effect." (PMID 37218983, 2023). "Increased infiltration of CAR T-cells into tumor.Reduction in tumor infiltrating Tregs.Suppression of co-inhibitory receptor (PD-1 & LAG3) expression on T cells.Promotes expression of T-cell recruiting chemokines in tumor cells (CXCL9, CXCL10) and CXCR3 receptors on CAR T cells." (PMID 36949946, 2023). "B cells can capture tumor antigens and activate immune cells in the initial stage of the immune response, or participate in tumor killing by secreting antibodies, such as CCL2, CXCR4, CCL5, CXCL5 and CXCL10, which trigger the activation of CD4 and CD8 T cells." (PMID 37254219, 2023). "CXCL10 further binds to CXCR3 on Tregs promoting their migration to the liver and facilitating the establishment of an immunosuppressive microenvironment that promotes tumor growth and recurrence after transplantation." (PMID 37345131, 2023). "Inactivating CAFs by inhibition of TGFβ in vivo also reduces collagen deposition, induces cell-mediated immune response with high expression of Th1 cytokines and chemokines CXCL9 and CXCL10, the recruitment of CD4+, CD8+ T-cells, and M1 macrophages to the tumor area." (PMID 37046676, 2023). "In contrast, the CXCL10-expressing cell line did not inhibit tumor growth, and the growth was similar to that of the Vector." (PMID 37218983, 2023). "CXCL10 and CXCL9 are antitumour chemokines that can inhibit cancer cell proliferation as well as regulate immunity to recruit a variety of immune cells to kill tumour cells." (PMID 36980202, 2023). "In glioblastoma cancer models, inhibition of the b-galactoside-binding lectin, galectin-1 has shown to enhance expression of CXCL10, CXCL12 and CCL5 resulting in recruitment of Gr-1+/CD11b+/CCR2+ myeloid cells which promoted the recruitment of tumor-infiltrating NK cells." (PMID 38022679, 2023). "Tumour necrosis percentage positively correlated with peripheral serum levels of CXCL8, a proinflammatory chemokine, and negatively correlated with mesenteric serum levels of CXCL10 and mast cell densities in the invasive margin of the tumour." (PMID 37031328, 2023). "However, CXCCL-9, CXCL10, and CXCR3 can have an opposite action in vivo where they increase tumor growth." (PMID 37296899, 2023). "The induction of CCL5 and CXCL10 chemokine expression induced by STING signaling appears particularly critical for recruiting immune effector cells such as CD8+ T lymphocytes and NK cells into the tumor microenvironment." (PMID 37079538, 2023).
tumor (continued). "Experimental evidence suggests that tumor-infiltrating cDC1s promote tumor control in various ways, including the production of chemokines such as C-X-C motif chemokine ligand 9 (CXCL9) and C-X-C motif chemokine ligand 10 (CXCL10), which recruit CD8+ T cells to the tumor site." (PMID 38012715, 2023). "Although the exact role of eosinophils in cancer is not fully understood, some studies suggest they contribute towards anti-tumor immunity by inducing tumor death via the production of anti-tumor factors such as TNF-α, along with recruiting CD8+ T cells into tumors via CXCL9 and CXCL10 release." (PMID 38137547, 2023). "In contrast, when compared to non-responders, responding tumours displayed more predicted interactions between CXCL10+ macrophages and the T cell compartment." (PMID 38030622, 2023). "CXCL10, CXCL13, and G-CSF were present at higher concentrations in the serum of tumor-bearing mice." (PMID 35013108, 2022). "However, a high ratio of CD8+ T cells within the tumor areas in relation to the total T cells in the stroma was correlated with the secretion of CXCR3 ligands (CXCL9, CXCL10 and CXCL11) and the CCR5 ligand CCL8." (PMID 35954489, 2022). "In addition, ppp-TGF-β with RIG-I activation also induced much more release of type I interferon and C-X-C motif chemokine ligand 10 (CXCL10), thus resulting in activation of CD8+ T cells and potent tumor cell apoptosis in orthotopic mouse model." (PMID 35652096, 2022). "We next hypothesized that the elevation in CXCL1, CXCL10 and CXCL13 in BTC patients might have a prognostic relevance following tumor resection." (PMID 36077611, 2022). "In addition, M1 macrophages secrete CXCL9, CXCL10 and CXCL15 chemokines upon STAT1 signaling, which recruit cytotoxic T lymphocytes (CTLs) to the tumor." (PMID 36311701, 2022). "Interestingly, we observed a tumor-independent enhancement of CD45+ cells in the CCl4 and DEN/CCl4-treated Cxcl10−/− mice compared to the WT counterparts." (PMID 35897689, 2022). "The initial serum levels of CXCL10 were significantly higher in patients with distal CCA compared to other tumor localizations but were unaltered between patients with different TNM stages, tumor grading or resection status." (PMID 36077611, 2022). "In addition, the immunoregulatory effect of CXCL9, CXCL10, and the CXCL11/CXCR3 axis on tumor sites to promote antitumor immunity has been used as a new tumor therapeutic target." (PMID 35754838, 2022). "While the production of CXCL10 was not investigated in CT26 or LL/2 tumor-bearing mice treated with cisplatin, the addition of the recombinant CXCL10 increases the antitumor effects." (PMID 36429101, 2022). "Tumor-intrinsic T-cell-exclusionary pathways typically converge on a repression of type I and/or II interferons (IFNs), and thence a paucity of IFN-induced T cell chemokines such as CXC-chemokine ligand 9 (CXCL9), CXCL10, and CXCL11 in the TME." (PMID 36531014, 2022). "As for the genes regulated by EBV-miRNAs, the CXCL9, CXCL10, CXCL11/CXCR3 axis has been found to regulate immune cell migration, differentiation, leading to tumor suppression and may have potential role in cancer treatment." (PMID 36544484, 2022). "Importantly, we found that SD70 monotherapy or dual combination therapy, our triple therapy showed the most substantial tumor-inhibitory effect in a CD8+ T cell dependent and CXCL10-dependent manner." (PMID 35121645, 2022). "First, it may be attributed to the trafficking of the antigen specific CD8 +T cells to the location of the tumor (as implied by the study with CXCL9 and CXCL10)." (PMID 35459734, 2022).
tumor (continued). "In summary, our results demonstrate that CXCL10 exerts a non-redundant impact on several hallmarks of the tumor microenvironment and especially modulates the infiltration of anti-tumorigenic immune cells in HCC." (PMID 35897689, 2022). "Since CXCR3 can bind to its ligands CXCL9, CXCL10, and CXCL11 to inhibit angiogenesis, CXCR3 may play an important role in wound healing and tumor growth." (PMID 36421704, 2022). "In addition, CXCL10 can induce CD8+ and CD4+ effector T cells to the tumor site and enhance their function." (PMID 35710862, 2022). "Our data revealed that the addition of TIGIT blockade to MWA upregulated the expressions of CXCL9 and CXCL10 in TAMs and the expression of their receptor CXCR3 in T cells, which might restrain tumor growth and enhance antitumor immunity." (PMID 35320940, 2022). "To summarize, TDO2+ myofibroblasts were mainly located distally from tumor nests, and these cells attracted CD4+ T cells and CD8+ T cells through the CXCL9/CXCL10/CXCL11/CXCR3 axis, which may have prevented T cells from accessing tumor nests." (PMID 35972800, 2022). "Interferon-α (IFN-α) stimulates the secretion of IP-10 (CXCL10), recruits effector T cells to the tumor microenvironment, and upregulates the expression of MHC-1 molecules on the surface of tumor cells, thereby enhancing the anti-tumor effects of CD8+T cells in the tumor microenvironment." (PMID 36125617, 2022). "CXCL10, in addition to inducing effector Th1 cells, also recruits CXCR3+CD8+ T cells to tumor sites and induces granzyme-b production through these cells, thereby enhancing the anti-tumor effect." (PMID 36479091, 2022). "Although CXCL10 shows no evident interconnection with TMPRSS2 in the PPI network, in PRAD patients, it has been linked to a group of tumor associated macrophages (TAMs) which are further classified into two different subtypes, M1 and M2." (PMID 36239108, 2022). "However, when we took into account the relative localization of T cells within the tumor, we also found a positive correlation between CXCL9, CXCL10 and a high CD8+ T cell ratio within and close to tumor nests." (PMID 35954489, 2022). "The use of epigenetic modulators (DNA methylation and H3K27 trimethylation inhibitors) restored the tumoural expression of CXCL9 and CXCL10, enhancing CAR T cell efficacy in a murine model of ovarian cancer, with improved T cell infiltration and tumour growth control." (PMID 35205725, 2022). "Numerous studies have modified MSCs to overexpress cytokines that potentiate immune responses against cancer, such as interleukin (IL)-12, C-X-C Motif Chemokine Ligand 10 (CXCL10), IFN-β or tumor necrosis factor alpha (TNFα), thus reducing tumor growth and improving survival." (PMID 35631698, 2022). "Combined with the observation that LINC01198’s activation in tumor cells increased IFN-γ, GzmB, and type I–related cytokine (i.e., CXCL10 and TNF-α) secretions, we hypothesized that LINC01198 regulated IFN signaling pathways in cancer cells." (PMID 36475797, 2022). "One hypothesis that warrants further study is that an increased chemotaxis of activated and tumor antigen-specific cytotoxic T-cells to the tumor, potentially via chemokines such as CXCL9 and CXCL10." (PMID 36532027, 2022). "(ii) Antitumor immune-related molecules including CXCL10, CXCL9, CXCR3, CCL5, and CCL4 belong to the chemokine family and have been reported in several studies to recruit immune cells such as cytotoxic T lymphocytes (CTL) and NK cells to kill tumor cells." (PMID 35479936, 2022). "The expression levels of CXCL2, CXCL10 and CXCL11 were related to tumor stage." (PMID 35181719, 2022). "In addition, CXCL9- and CXCL10-expressing Macro-2 tumor cells interact with CXCR3-expressing proliferating T cells, Tregs, and CTL-1 cells in the tumor." (PMID 36180422, 2022).
tumor (continued). "IFN-γ-inducible CXCL9, CXCL10 and CXCL11 are chemokines for the activation of cytotoxic T cells, which attract more cytotoxic T cells to infiltrate into tumor tissues and exert anti-tumor effects." (PMID 35300424, 2022). "Next, we set out to assess the functional impact of Cxcl10 expression on tumor burden in mice by subjecting mice with or without genetic deletion of Cxcl10 to our tumor model." (PMID 35897689, 2022). "Under the chemotactic effect of CXCL9, CXCL10, and CXCL11, activated Th1 cells reach the tumor site to exert phagocytosis and upregulate CXCL9, CXCL10, and CXCL11 secretion, thus recruiting more T lymphocytes to participate in the immune response at the lesion site." (PMID 36479091, 2022). "In support of this, in mouse lung cancer, also IL-33 was related to good prognosis since it could elevate the frequency of tumour infiltrating ILC2s via CCL5, CXCL10, and CXCL12." (PMID 35406451, 2022). "In this context, for the first time, we found that GSK343 treatment was able to modulate the innate immune response, increasing CXCL9, CXCL10 and CXCL11 levels in GB, as a result of EZH2 inhibition, enhancing NK cell migration to tumor sites and consequently NK cell-mediated tumor growth inhibition." (PMID 36430394, 2022). "Accordingly, these data provide strong evidence that B3GALT4 overexpression may promote CD8+ T lymphocyte recruitment into tumor sites via CXCL9 and CXCL10 in NB." (PMID 36284313, 2022). "In concurrence with NanoString analysis of our own tumor samples, these included IFN-γ signaling genes STAT1, CXCL10, and IDO1; antigen presentation molecules HLA-DQA1 and HLA-DRB1; important T cell molecules GZMB and IL7R; and B cell–related molecules CD79A and CXCL13." (PMID 35132960, 2022). "Depletion of METTL3 or METTL14 in tumor cells increased cytotoxic tumor-infiltrating CD8+ T cells and elevated secretion of IFN-γ, CXCL9, and CXCL10 in the TME, thereby enhancing the response to anti-PD-1 treatment in mismatch-repair-proficient or microsatellite instability-low CRC tumors." (PMID 35296338, 2022). "CXCL10, CXCL11/CXCR3 axis can be used as the target of tumor immunotherapy." (PMID 35432485, 2022). "Finally, a single injection of cyclophosphamide, a drug able to induce ICD, can increase the Cxcl9, Cxcl10 and Cxcl11 expression within mastocytoma tumors (an effect dependent on CD4 T cells), thus allowing the recruitment of CD8 T cells and tumor regression." (PMID 36429101, 2022). "Genome-wide studies showed that EZH2 levels are negatively correlated with CD8+ T cells, mainly inhibiting the production of tumor TH1-type chemokines CXCL9 and CXCL10 and thus reducing the recruitment of T cells, while the binding of carboxyl structure of ARID1A to EZH2 can reverse this step." (PMID 36713412, 2022). "The collective evidence therefore suggest that SPATA2 over-expression is associated with a non-T-cell-inflamed TME in CRC, and that SPATA2 might mediate T cell exclusion by inhibiting the production of CXCL9, CXCL10, and CXCL11 from tumor cells." (PMID 36531014, 2022). "qRT-PCR showed that L. paracasei sh2020 made a drastic increase in the level of CXCL10 in tumor tissue, whereas no changes were found in CXCL9, and CXCL11." (PMID 35259052, 2022). "We found that cisplatin-pretreated tumor cells stimulate neutrophils which expressed higher levels of cytotoxic effectors, including TNF-α, GZMB, and ELANE, and pro-inflammatory cytokines, such as CCL2, CCL3, CXCL10, CXCL11, and IL12." (PMID 35784745, 2022). "Due to their unstable genomes, these cells produce particular cytoplasmic DNA fragments (at baseline or under chemotherapeutic treatments) which sense the cGAS/STING and type I IFN signaling pathways to induce the production of CXCL10 and CCL5 and the recruitment of CD8 T cells at the tumor site." (PMID 36429101, 2022).